CD33 (CD33 molecule)
Diseases named in the same sentence as CD33 in open-access papers (continued):
Sharing a sentence is not in itself a finding about the gene and the disease.
tumor (continued). "Tumor analysis of the microPET data using VOIs showed significant blocking of 89Zr-lintuzumab in the group pre-treated with naive lintuzumab (pre-blocked group), thus indicating specific targeting of CD33 on OCI-AML3 cells in vivo." (PMID 36235126, 2022). "designed Caspase9-CAR CD33T cells inducibly selected by ΔCD19, which could specifically lyse CD33+ MV4-11 tumor cells and primary leukemic blasts in vitro, following which CAR-T cells were largely eliminated by suicide gene activation." (PMID 36523990, 2022). "In cervical cancer (CC), METTL3 was expressed much more highly in tumor tissues than in tumor-adjacent tissues, and its level was positively related to the density of CD33+ myeloid-derived suppressor cells (MDSCs), which in turn was linked to poor patient survival rate." (PMID 35296338, 2022). "This phenotype could correspond to antigen presenting cells-like hybrid tumour associated neutrophils (APC-like TAN) in which markers for both granulocytes (CD11b, CD66b, CD15) and monocytes (CD33, CD14, HLA-DR, CCR7, CD86, CD20) co-exist." (PMID 36189320, 2022). "Since CD33 and CD123 are not exclusively expressed on AML blasts but also on progenitor and mature hematopoietic cells of the myeloid lineage, conventional CD33- and CD123-specific CAR T-cells mediate impressive anti-tumor responses but also bear the risk for long-lasting cytopenias." (PMID 34638268, 2021). "In order to overcome tumor escape variants, universal RevCAR T-cells can be flexibly adapted to target CD33 or CD123 AML markers without re-engineering of T-cells." (PMID 34638268, 2021). "However, here we emphasize that both RevTMs targeting either CD33 or CD123 mediate a highly efficient tumor cell lysis in the pM range." (PMID 34638268, 2021). "The CD33 group of Siglecs was found to play a major role as immune checkpoint molecules in the tumor-microenvironment of BC: inhibiting Siglec-7 (expressed on eosinophils and Natural killer (NK) cells) could induce NK cell lysis of tumor cells." (PMID 33670444, 2021). "Similar to BiKEs, there are two scFVs: CD16 engages NK cell and CD33 binds tumor cells." (PMID 34071099, 2021). "A visible group of TAMs and CD33-positive myeloid cells were also observed in most tumor tissues." (PMID 34257571, 2021). "CD33 is expressed on a heterogenous population of myeloid cells, and it does not distinguish MDSCs from TAMs or tumor-associated neutrophils (TANs)." (PMID 33000418, 2021). "Therefore, we sorted CD33high cells to avoid other cells expressing dim or low levels of CD33 from tumor tissues of CRC patients with varying disease stages to perform RNA-Seq." (PMID 33000418, 2021). "Because CD16 is the most potent activating receptor on NK cells, this single agent may induce a targeted cytolytic anti-CD33 tumor response." (PMID 34521810, 2021). "There was a significant anti-tumor response leading to the depletion of CD33+ blast cells." (PMID 34071099, 2021). "Moreover, we identified a unique “poor prognosis CD33+ gene signature” by aligning top upregulated and downregulated genes in tumor-infiltrating myeloid cells from our analyses with data from The Cancer Genome Atlas." (PMID 33000418, 2021). "CD7– T cells could be manufactured into CD19- and CD33-targeting CAR T cells that were able to kill tumor cells expressing the target antigen." (PMID 34423790, 2021). "Notably, gemtuzumab ozogamicin, a novel anti-CD33 antibody drug conjugate, has emerged as a propitious treatment strategy to effectively deplete MDSCs in various tumor types and augment anti-tumor immune responses in a clinically relevant manner." (PMID 35011582, 2021). "Our study demonstrated a comprehensive result of the relationship between METTL3 and CD33 in CC and revealed that METTL3 could induce direct MDSC and tumour-associated MDSC differentiation in vitro." (PMID 33059689, 2020).
tumor (continued). "Microscopic analysis showed a higher level of cells that were positive for STAT, pSTAT3+, and CD33+ in BC tissues compared to tumor-adjacent normal tissues and normal breast tissue, suggesting the passage of MDSCs from blood circulation into the BC tumor microenvironment." (PMID 33679700, 2020). "We first assessed whether CD33+/HLA-DR−/EMCs and its subpopulations are enriched in blood samples and tumor tissue of cancer patients compared to healthy donors." (PMID 32903466, 2020). "In addition, increased percentages of CD33+S100a9+ cells in BTC tumour tissue correlated with higher tumour grade, the presence of satellite lesions, and more poorly differentiated tumours." (PMID 32747748, 2020). "However, only a few CD33-CD11b+MDSCs in tumor tissues expressed ARG1 (0.63 ± 0.29% vs 0.17 ± 0.12%) (p > 0.05)." (PMID 32415175, 2020). "Expression of VISTA on CD33-positive MDSCs could enhance their immunosuppressive function, resulting in tumor progression." (PMID 32873829, 2020). "Therefore, for in vitro mimicking of the tumor microenvironment, we used a Transwell co-culture system in vitro, connecting carcinoma cells and CD33+ myeloid cells." (PMID 32632113, 2020). "Here, our data suggest that METTL3-mediated m6A RNA modification is positively associated with the increase in MDSC expansion and affects tumour development and prognosis in CC and induces CD33 + cells to differentiate into MDSCs in the tumour microenvironment." (PMID 33059689, 2020). "Moreover, in human liver cancer, CD33+M-MDSCs are obviously enriched in the fibrotic liver near the tumor." (PMID 32942545, 2020). "In addition, we analysed the relationship between METTL3 expression in tumour cells and in tumour-infiltrating immune cells and the number of CD33+ MDSCs via Spearman’s correlation coefficient and linear regression." (PMID 33059689, 2020). "This suggested that NK cells acquired CD14 by trogocytosis on tumor AML cells as they gained CD33." (PMID 33276644, 2020). "Importantly, METTL3 expression was positively related to the density of CD33+ cells in tumour tissues (P = 0.011)." (PMID 33059689, 2020). "Previous evidence has shown CD33+ myeloid cells may be composed of both tumor-resident myeloid-derived suppressor cells (MDSCs) and activated neutrophils." (PMID 32150594, 2020). "However, when comparing all anti-CD33 Nbs, Nb_7 showed the highest tumor uptake (2.53 ± 0.69%IA/g), with the lowest background signal." (PMID 31906437, 2020). "For AML or MDS, combination of magrolimab with tumor-targeting antibodies against leukemic antigens such as CD33 or CD123 may be efficacious." (PMID 32038992, 2019). "However, CD33 is a normal myeloid surface antigen that likely requires gene editing to avoid myeloablative toxicity and severe CRS driven by on-target/off-tumor action of CD33 CAR-T cells." (PMID 30941303, 2019). "HLA‐DR−CD11b+CD33+ MDSCs were isolated from tumor tissues from CRC patients." (PMID 31559140, 2019). "iCasp9 suicide gene and ΔCD19 modified CD33 CAR-T cells (iCasp9/CAR CD33/ΔCD19) not only are cytotoxic to CD33-positive tumor cells but also could be used as a “bridge” therapy for patients coming to allo-HSCT." (PMID 31429760, 2019). "In cancer, MDSCs (CD34+CD33+CD13+CD15(−)) promote tumor cell growth and suppresses immune cell function through production of arginase 1 (ARG1) which synergizes with inducible nitric oxide synthase (iNOS) to increase superoxide and nitric oxide (NO) production, thus, reducing lymphocyte function." (PMID 31430935, 2019). "Flow cytometry and immunohistochemistry of blood and tumours determined MDSC CD33 expression." (PMID 31462392, 2019). "Thus CD33 is expressed on the MDSCs pathologically expanded in the blood and tumour tissues of adults and children with cancer and which create an immunosuppressive microenvironment." (PMID 31462392, 2019).
tumor (continued). "Sialic acids in tumor cells form ligands for CD33-related Siglecs which trigger suppressive signalling to immune cells via tyrosine-based inhibitory motifs (ITIM) and SHP1/SHP2 molecules that modulate cytotoxic and inflammatory responses leading to increased pathology development." (PMID 30443853, 2019). "To determine whether CAR33VH targets the full length CD33, we created A431-luciferase-positive tumor cells stably expressing either the full length CD33, termed CD33M, aka CD33v1, or the truncated form CD33m, aka CD33v2." (PMID 30524966, 2018). "This corresponds to a greater induction of IFN-gamma, TNF-alpha and IL-2 in response to MOLM-14 as compared to HL-60 tumor cells, and a greater induction in response to HL-60 vs. KG-1a, and also correlates with the relative cytotoxic activity of the anti-CD33 CARs against these cell lines." (PMID 30524966, 2018). "An initial clue supporting this hypothesis was provided by immunohistochemical (IHC) analyses of tumor sections; the abundance of CD33+ MDSCs was correlated to the level of LMP1 and glucose transporter 1 (GLUT1) expression in malignant epithelial cells." (PMID 28732079, 2017). "BiTEs have been designed to target a variety of tumor antigens such as CD19, EphA2 receptor tyrosine kinase, EpCAM, EGFR, melanoma-associated chondroitin sulfate proteoglycan, and CD33, among others, and have shown therapeutic efficacy in mouse tumor models." (PMID 28938530, 2017). "LicMABs and antiCD33 mAb preferentially induced lysis of MOLM-13 cells in comparison to OCI-AML3 cells at both concentrations evaluated (10 μM and at the EC50), indicating that cells expressing high levels of CD33, such as tumor cells, are preferentially cleared." (PMID 28061465, 2017). "Since CD47 is overexpressed on cancer cells with respect to normal cells, we propose that the SIRPα domain of the licMAB would not bind to normal cells expressing CD47 but facilitate the targeting of dual antigen-expressing tumor cells led by high affinity binding to CD33." (PMID 28061465, 2017). "Furthermore, we found a significant increase in the levels of CD33+CD11b+HLA-DR−/lowCD14−CD15− cells identified as IM-MDSC in tumor tissue (NT; 0.5 ± 0.2 vs TT; 7.8 ± 3.5)." (PMID 28283696, 2017). "Although licMABs induced cytotoxicity and phagocytosis of CD33 positive tumor cells, antitumor immune responses might be even greater if internalization would not occur." (PMID 28061465, 2017). "We hypothesized that the high affinity for CD33 of the licMABs would facilitate preferred tumor antigen-binding over healthy CD47-expressing cells." (PMID 28061465, 2017). "Although the resulting molecule would not retain the favorable avidity effects of a mAb and may therefore have a lower affinity towards CD33, monovalent targeting of CD33 might reduce internalization and this may enhance elimination of tumor cells." (PMID 28061465, 2017). "Antigen down-regulation was not the implicated mechanism of tumor evasion, since the patient blasts still highly expressed CD33 at progression." (PMID 27907031, 2016). "Furthermore, an increase in CD33+CD11b+HLA-DR−CD14−CD15− immature myeloid cells was also observed in CRC tumor tissue." (PMID 28008330, 2016). "Despite the high amount of unconjugated antibody, which could reduce its effectiveness, Mylotarg was able to kill CD33 expressing cells in in-vitro cytotoxicity studies and in preclinical in-vivo tumor efficacy studies." (PMID 25339341, 2015). "The anti-tumor effect of CD33 retargeted T cells can be reinforced by co-stimulation with 4-1BBL." (PMID 26383821, 2015). "We asked whether addition of MDSC to ATC would suppress the ability of ATC to produce IFN-γ when stimulated with MiaE targets at a 1:10:2 ratio (Tumor cell:ATC:CD33+) for 4 hrs." (PMID 23394575, 2013). "Likewise, the cytotoxicity mediated by aATC directed at SK-BR-3 targets was inhibited by 70% at 1:10:2 ratio (Tumor cell:aATC:CD33+) after adding CD33+ cells isolated from control conditions." (PMID 23394575, 2013).
tumor (continued). "This is particularly relevant in light of the frequently and severe reported hepatic toxicity related to the addition of a toxic compound to the CD33 targeting and subsequent calicheamicin accumulation and/or unwanted release and toxicity to normal cells surrounding CD33+ tumor cells." (PMID 22272203, 2012). "Treatment of either CD33+ or CD11b+ tumor-cell line-induced MDSC with lipopolysaccharide, a known activator of MDSC function, caused further up-regulation of STAT3, C/EBPβ, and HIF1α concurrent with increased expression of ARG-1, iNOS, and NOX2-component NCF1 (data not shown)." (PMID 21658270, 2011). "CD33+ or CD11b+ MDSC may be induced under a variety of different tumor conditions and following incubation with several distinct cytokine mixtures." (PMID 21658270, 2011). "However, it remains essential to confirm whether these CD33+ cells functionally resemble their tumor-infiltrating counterparts, as mere phenotypic presence without validated suppressive activity may not fully capture the complexity of the HNSCC immune milieu." (PMID 40508078, 2025). "Early studies using beta-particle emitters such as Iodine-131 and Yttrium-90 conjugated to anti-CD33 antibodies (M195 and huM195) demonstrated some reduction in leukemic burden, but their therapeutic impact was modest, especially in patients with high tumor loads." (PMID 41282197, 2025). "Interestingly, aITGB2 expression remained high (greater than 95%) in the CD33/CD45-positive tumor population in bone marrow, including single-or fractionated-dose [225Ac]Macropa-PEG4-7065 groups, [225Ac]DOTA-anti-CD33, [225Ac]Macropa-PEG4-IgG, saline + IgG injected groups." (PMID 41282197, 2025). "Furthermore, this molecule exhibited efficacy even if one of the target antigens (CD19 or CD33) was not present on the tumour cell, providing a potential safety net against antigen loss variants commonly seen after targeted therapies." (PMID 39472273, 2024). "This safety aspect, as it pertains not only to on-target, on-tumor toxicity but also on-target, off-tumor toxicity, may be particularly important for a myeloid differentiation antigen such as CD33 that is broadly expressed not only on AML cells but also on normal maturing and mature myeloid cells." (PMID 38473239, 2024). "Finally, the specificity of CD33-CAR NK cells was tested against CD33+ tumor cells: the RS4;11 tumor cell line was killed by CD33-CAR NK cells with high efficiency when expressing CD33, whereas a variant that did not express CD33 (GFP+RS4;11) was not recognized." (PMID 35058934, 2021). "Accordingly, we evaluated the correlation between CD33+ MDSCs and PD-1−PD-L1+ Bregs and observed an obvious positive correlation, indicating that MDSCs may educate PD-1−PD-L1+ Bregs to exert immunosuppressive effects in tumor tissues." (PMID 33967272, 2021). "Expressed on most of the MDSCs, CD33 could be an interesting target in the tumor microenvironment." (PMID 32521744, 2020). "We further demonstrated that the percentage of CD33+CD11b+HLA-DR− peripheral MDSCs was increased in CC patients compared with healthy donors, as was the percentage of tumour-derived CD33+CD11b+HLA-DR− MDSCs compared with that of tumour-adjacent tissues (n = 3)." (PMID 33059689, 2020). "Moreover, after treatment, when tumor targets are sparser, CD33 decreases in patients’ NK cells." (PMID 33276644, 2020). "Similarly to normal/reactive MC, tumor BMMC from SM patients were also systematically positive for CD33 (100%, p > 0.05) on their surface membrane, at similarly high and homogenous levels as evaluated by the stain index (SI) and its coefficient of variation within individual cases (data not shown)." (PMID 30696068, 2019). "Together, these observations suggest that targeting CD33+ myeloid cells, using agents such as Gemtuzumab ozogamicin, could potentially augment immune checkpoint therapy by eliminating immunosuppressive cells from the tumor microenvironment." (PMID 31395880, 2019).
tumor (continued). "The cell types and markers we explored were as follows: tumor epithelial cells (E-cadherin as a marker), cancer-associated fibroblasts (CAFs; Collagen1A1), endothelial cells (Von Willebrand Factor [VWF]), the immune compartment (CD45), T cells (CD3G), myeloid cells (CD33), and macrophages (CD14)." (PMID 31765370, 2019). "In patients <75 years, the density of TAICs, except for the CD33+ density, exhibited a positive significant correlation with expression of PD-L1 in tumor cells, whereas we found a lower correlation of PD-L1 expression in tumor cells with TAICs marker density in elderly patients ≥75 years." (PMID 30216999, 2018). "Thus, to confirm whether RUNXOR was expressed in MDSCs, we not only isolated CD11b + CD33 + HLA-DR-CD14- MDSCs from tumor tissue but also induced CD33+ MDSCs from PBMCs of healthy donors, and then detected the expression of RUNXOR in these MDSCs." (PMID 29914443, 2018). "As a result, notable CD33+ target cell killing was detected via standard chromium release cytotoxicity assays already after 24 h, leading to approximately 50% to 70% of tumor cell lysis after 48 h of incubation in the presence of bsAb-releasing or bsAb-releasing/4-1BBL-expressing MSCs respectively." (PMID 28205621, 2017). "Taken together, CD33-dependent internalization of licMABs could be overcome by different strategies, which should be further explored in order to have a maximal effect on tumor clearance." (PMID 28061465, 2017). "Consequently, the binding properties of licMABs enable them to selectively bind to CD33-expressing tumor cells in the presence of excess of RBCs expressing CD47, thus overcoming the antigen sink that RBCs may represent." (PMID 28061465, 2017). "PMN‐MDSCs, especially CD11b+CD14− and CD33+CD14− cells, were correlated with advanced tumor stage (T2 and T3), cancer stage (stage II and III), and the TNBC subtype." (PMID 39749673, 2025). "Bicistronic CD33/CLL-1-CAR-T cells were given to two AML patients, both achieving MRD-negative CR after two infusions (one of them after only 19 days), proving anti-tumor potency and effectiveness." (PMID 41310898, 2025). "These subpopulations exhibited differential expression of surface tumor antigens, including the CAR target (i.e., CD33), the NKT TCR target (i.e., CD1d), and NKR ligands (i.e., CD112, CD155, and MICA/B)." (PMID 39893165, 2025). "At present, the clinical development of antibodies is mainly aimed at targeting tumor-related antigens (TAA, such as CD19, CD20, CD22, CD30, CD33, BCMA, and other targets)." (PMID 40244018, 2025). "These include targets expressed in hematological malignancies (such as BCMA, CD19, CD20, CD13, CD38, CD33, CD72, and CD7), solid tumors (such as PSMA, FGFR4, and GPC2) and tumor microenvironment (such as VEGFR2, EIIIB, PD-L1, and CD105)." (PMID 40474230, 2025). "Most approved ADCs currently focus on targets such as HER2, CD30, CD33, and TROP2, which are characterized by high expression in malignant tissues, efficient internalization, and relevance to tumor biology." (PMID 41184856, 2025). "Allo15CAR33-NKT cells are expected to target myeloid malignancy tumor cells through multiple surface receptors, including CAR33-mediated recognition of CD33, NKT TCR-mediated recognition of CD1d, and NKR-mediated recognition of NK ligands." (PMID 39893165, 2025). "To test CD33 | CD16b Tmod cells in vivo, we utilized a xenograft model based on growth of the AML line MV-4-11 in NSG mice after intravenous infusion of tumor cells." (PMID 40191207, 2025). "Following preconditioning with busulfan and PDX tumor inoculation, treatment was initiated on day 10 with treatment arms including vehicle, [225Ac]DOTA-anti-CD33, and [225Ac]Macropa-PEG4-7065 group." (PMID 41282197, 2025). "About 40% of myeloid cells (CD33+) and ~10% of B cells (CD19+) also expressed PD-L1, reinforcing a multifaceted immunosuppressive network within the tumor." (PMID 40860824, 2025).